IL10 (interleukin 10)
Diseases named in the same sentence as IL10 in open-access papers (continued):
Sharing a sentence is not in itself a finding about the gene and the disease.
tumor (continued). "The elevated production of IL-10 by IL-1β-induced MDSCs and down-regulated production of IL-12 converted tumor immunity from a tumor-rejecting type 1 response to a tumor-promoting type 2 response, which promotes tumor growth." (PMID 29029545, 2017). "Further the Tregs isolated from animals maintained on the KD produced significantly less IL-10 when stimulated with tumor cells." (PMID 27178315, 2016). "The frequencies of tumor-infiltrating IL-10-expressing B cells and the frequencies of granzyme A and perforin-expressing CD4+ T cells were negatively correlated." (PMID 27136203, 2016). "Several different phenotypes of regulatory B cells (Bregs) have been reported, including the B10 cell, which regulates anti-tumor responses via IL-10 production." (PMID 27121060, 2016). "Mechanistically, it was revealed that the tumor is able to instruct intratumoral macrophages to overexpress and secrete Gas6 by releasing Interleukin-10 (IL-10) and Macrophage colony-stimulating factor (M-CSF) into the microenvironment." (PMID 27775650, 2016). "Conversely, IL-10 levels were suppressed in LLC tumour bearing mice by both s.c. administration and IV." (PMID 27412241, 2016). "Within the group of 17 proteins, four exhibited the most pronounced expression difference: IGFBP7, S100A9 and IL-10 were found strongly up-regulated in tumor, while MUC6 was markedly less abundant compared to the reference tissue." (PMID 27600085, 2016). "We demonstrate that HMGB1 released by hypoxic tumour cells favours the accumulation of M2-like macrophages at the tumour site and their secretion of IL-10." (PMID 27426915, 2016). "Suppression by the tumor microenvironment is mediated by a unique subset of CD4+CD25highFoxp3+ Tregs that produce IL-10 and TGF-β, which lead to a more antiproliferative effects." (PMID 27044404, 2016). "Mounting evidence supports a potent inhibitory role of interleukin-10 (IL-10) in tumor carcinogenesis, angiogenesis and metastasis." (PMID 27489033, 2016). "Immunization together with IL-10 inhibition further improves clearance of chronic viral, bacterial infection and prevent tumour growth." (PMID 27100390, 2016). "Serum levels of IL-6, IL-8 and IL-10 were measured before surgery and anaesthesia, during tumour removal, at the end of surgery, and at 24 and 48 h after surgery." (PMID 27001425, 2016). "Therefore, induction of activated FcγRIIlow/− IL-10-producing B cells by semimature DCs, which are differentiated from tumour-activated monocytes, may represent a mechanism by which the immune activation is linked to immune tolerance in the tumour milieu." (PMID 27853178, 2016). "Tumor derived cytokines such as IL-4, IL-10, IL-13, TGFβ and prostaglandin E2 can drive the production of M2 macrophages while IL-12 is produced by M1 macrophages." (PMID 26654940, 2016). "In this study, we found that laricitrin not only enhances DCs’ function, increasing IL-12 and decreasing IL-10 expression, but also switches tumor-promoting Th2 to a tumor-destructive Th1 response in vivo." (PMID 27833081, 2016). "Although there are no significant changes in the expression of pro-inflammatory cytokines, such as TNF-α, TGF-β, INF-γ and IL-6, we found a significant overexpression of the anti-inflammatory cytokine IL-10 within the tumor mass of B1−/− mice." (PMID 26898917, 2016). "In order to define the functional consequences of MΦ-polarization in terms of iron sequestration versus release, we checked the proliferation rate of tumor cells, which were stimulated with supernatants of LPS/IFNγ- or IL-10-treated MΦ." (PMID 27806101, 2016). "In contrast, tumor progression is paralleled by a reduction in Nrp-1-producing Tregs controlled by the IL-10 and TGF-β1 levels." (PMID 27075020, 2016). "Antigen-stimulated Tregs secrete TGF-β, thereby enabling tumor growth; this growth is dampened by Nrp-1+ Tregs concomitant with the presence of IL-10." (PMID 27075020, 2016).
tumor (continued). "In accordance with this finding, FACS analysis showed that both M1 (IL-12+) and M2 (IL-10+) macrophages were increased in sST2 low-expressing tumours compared with sST2 high-expressing tumours." (PMID 27882929, 2016). "Tumour culture supernatant (TCS) increased the secretion of IL-10, one of the M2 phenotype markers, and decreased the secretion of IL-12 and TNF-α, M1 phenotype markers, in the HMDMs." (PMID 27404320, 2016). "We conclude that Nrp-1 is highly expressed by Tregs that control Foxp3+ Treg migration into the tumor, and this process is highly dependent on tumor-derived IL-10." (PMID 27075020, 2016). "Dabigatran etexilate, with or without cisplatin, also reduced the levels of the proinflammatory cytokines MCP-1, IL-6 and IL-10 in the ascites of ID8 tumor bearing mice." (PMID 27852034, 2016). "Compared to that in peripheral blood, the level of IL-10-expressing B cells were further upregulated in resected tumor, while the level of CD4+ cytotoxic T cells was downregulated." (PMID 27136203, 2016). "Interferon gamma (IFNγ) and IL-10 are considered hallmark cytokines for antitumour TH1 responses and immunological tumour tolerance, respectively." (PMID 27990285, 2016). "IL10 and the gene encoding its receptor IL10R were expressed mainly by TAMs, LIF and LIFR by tumor cells, IL6 and the genes for IL6 receptor subunits IL6R and IL6ST by both cell types." (PMID 27215396, 2016). "Other cytokines are involved in such process like interferon gamma (IFN-γ) and IL-10 that are produced by tumour microenvironment." (PMID 26801617, 2016). "Recently, PGE2 has been implicated in the enhancement of protumorigenic Th2-type cytokine, such as IL-4, IL-5, and IL-10, and inhibition of the anti-tumor Th1 cytokine production, such as IFN-γ and IL-2." (PMID 28053982, 2016). "The M2b phenotype is induced by LPS and immune complexes and the M2c by IL-10 and TGF-β, whereas the M2d is applied to tumour associated macrophages which typically display M2-like properties." (PMID 27359332, 2016). "Exposure of macrophages to hyaluronan, either purified or tumor-derived, leads to increased expression of various inflammatory mediators including IL-1β and IL-10." (PMID 26884646, 2016). "It is also a well-known fact that STAT activation is generally mediated by members of the JAK family of tyrosine-kinases via stimulation of NF-κB regulated genes such as IL-6, IL-10 and IFNγ which are produced by tumor cells in an autocrine manner." (PMID 26998758, 2016). "IL-10 is a cytokine produced by Th1 and Th2 cells as well as by tumor cells and has potent immunosuppressive properties." (PMID 26989335, 2016). "Treatment of the IL-10−/− B16/F10 mice with anti-Nrp-1 significantly reduced the tumor volumes in tumor-bearing mice." (PMID 27075020, 2016). "The results show that INFα-2b inhibits cancer cell immune evasion by decreasing the levels of CD4+CD25+Foxp3+ Tregs and suppressing the expression of TGFβ and IL-10 in the tumor microenvironment." (PMID 27389040, 2016). "As a countermeasure, NSCLC tumor cells secrete cytokines such as IL‐10, which promotes regulatory T‐cell (Treg) proliferation and suppresses CD8+ T‐cell‐mediated cytotoxic killing." (PMID 27416962, 2016). "In early studies of immune regulation within the tumor microenvironment, we found that the immune regulating cytokine IL10 was overexpressed in biopsies of melanoma lesions in patients." (PMID 28191451, 2016). "Doxycycline-induced EGFRL858R mice treated with gefitinib and anti-IL10 antibodies exhibited poor tumor formation." (PMID 26956044, 2016). "Interleukin-10 (IL-10) is a multifunctional cytokine with both immunosuppressive and antiangiogenic functions; thus, it has both tumor-promoting and tumor-inhibiting properties." (PMID 27375834, 2016). "After treatment, the level of Tregs in the spleen and in peripheral blood, and the levels of TGFβ and IL-10 in the tumor microenvironment were determined." (PMID 27389040, 2016).
tumor (continued). "M2 macrophages activated by direct contact with EOC cells secrete several cytokines such as IL-6 and IL-10, which in turn induced tumour cell activation." (PMID 27404320, 2016). "In contrast, they were positive in 26 (54.2%) and 23 (47.9%) of PCNSL (vs systemic DLBCL, P < 0.001), and in most positive cases, both Tim‐1 and IL‐10 were stained in more than 80% of the tumor cells." (PMID 27709813, 2016). "The neutralization of Nrp-1 in the IL-10−/− or WT B16/F10 mice resulted in elevated tumor-derived CD8a+ or IFN-γ protein expression in CD8+ T cells." (PMID 27075020, 2016). "Flow cytometry was used to determine the Tregs levels in the spleen and peripheral blood, and immunohistochemistry was performed to determine the expression levels of TGFβ and IL-10 in the tumor microenvironment." (PMID 27389040, 2016). "In a study using three mouse prostate cancer models, IgA-producing plasmocytes express programmed death ligand 1 (PD-L1), IL-10, and Fas-L, and thus inhibited T-cell-dependent tumor eradication." (PMID 27331871, 2016). "In this model, B16-F10 melanoma induces accumulation of T2-MZP Bregs in TDLN, which in turn promote tumor growth and metastasis, and appear to do so independently of IL-10 and/or Tregs." (PMID 27437104, 2016). "Thereafter, the FcγRIIlow/− activated B cells operate via IL-10-dependent pathways to induce T-cell suppression and thereby create circumstances that are favourable to tumour growth." (PMID 27853178, 2016). "A large amount of molecules released by tumor cells or tumor-surrounding cells, including IL-1β, IL-4, IL-6, IL-10, IFN-γ and TGF-β, are reported to re-program immature myeloid cells to become immunosuppressive." (PMID 26967390, 2016). "TAMs generally acquire an M2-like phenotype, presenting high levels of IL-10 and low levels of IL-12 that play a crucial role in tumor progression." (PMID 27102437, 2016). "The Th2 cytokines IL-4 and IL-10 suppress the generation of CTLs and Th1 cells and recruit tumour entry of Tregs." (PMID 27777963, 2016). "Immunohistochemical staining of the serial sections and fluorescent double staining analysis indicated that Tim‐1 and IL‐10 were coexpressed in tumor B cells, and a moderate correlation was observed between their positivities (Cramer's V = 0.55, P < 0.001)." (PMID 27709813, 2016). "As an important modulator of immune responses, IL-10 can be both tumor-promoting and tumor-inhibiting since it has both immunosuppressive and anti-angiogenic functions." (PMID 27995011, 2016). "IL-10 suppresses anti-tumor immunity while T cell-derived IL-10 promotes cancer growth by suppressing both T cell and APC function." (PMID 26754564, 2016). "Jindal and Borges showed that IL-10 inhibits tumor growth by preventing chemokine expression and angiogenesis when administered at higher doses in cancer animal models." (PMID 26989335, 2016). "In miliary, a shift of the immune system from tumor surveillance to pro-tumorigenic actions seems possible, supported by the increased presence of B-cells and elevated IL-10 concentrations in the ascites." (PMID 27665539, 2016). "IL-10 has been shown to inhibit T helper cell production, impair dendritic cell maturation and inhibit T cell co-stimulatory molecules, suggesting that IL-10 in the ascites helps shield tumor cells from immunosurveillance." (PMID 27852034, 2016). "Expression of TGFβ and IL-10 in the tumor microenvironment in the CT and RT groups was higher compared with the control group (P < 0.01), while the expression of TGFβ and IL-10 in the INFα group was not significantly different (P > 0.05)." (PMID 27389040, 2016). "Inhibition of TGF-β or IL-10 resulted in decreased Nrp-1 expression in tumor tissue and reduced tumor-derived VEGF." (PMID 27075020, 2016). "In established tumors MDSC-, T-reg- or TAM-derived IL-10, found in high concentration in the tumor microenvironment, stimulate TAMs to convey inhibitory signals to T-cells through the expression of B7-H1 (PD-L1) and B7-H4." (PMID 27886105, 2016).
tumor (continued). "Although IL-10 has been reported as a cytokine related to M2, IL-10 is drawing attention as an inhibitor of tumor angiogenesis." (PMID 27157642, 2016). "On day +15, the tumor-secreted TGF-β1 levels in the IL-10−/− and WT B16/F10 mice were both significantly reduced after TGF-β neutralization." (PMID 27075020, 2016). "Conditioned media from cancer cells increases migration of M2 cells, and the tumor microenvironment encourages M2 differentiation through IL-10 secretion." (PMID 26998523, 2016). "SCID mice injected with human MHCC-97 L HCC cells mice together with human CD19+CD24+CD38+ Bregs demonstrated markedly larger tumor growth at 6 weeks and increased serum IL-10 levels compared to SCID mice injected with HCC cells and CD19+CD24−CD38− non-Bregs." (PMID 27437104, 2016). "It is plausible that IL-10 serving as a positive feedback during B-cell activation in cancer environments is utilized by tumours to suppress cytotoxic T-cell functions." (PMID 27853178, 2016). "PD-L1 containing tumor cells can induce T cell apoptosis, IL-10 production and can protect tumor cells from lysis by cytotoxic T lymphocytes (CTLs)." (PMID 27086918, 2016). "The PD-L1/PD-1 pathway has been demonstrated to inhibit the T-cell anti-tumour immune response, and PD-L1 preferentially co-stimulates IL-10 production in T cells." (PMID 27147225, 2016). "Splenic CD4+Foxp3+ T cells and tumor CD4+Foxp3+ T cells obtained from IL-10−/− B16/F10 mice were significantly increased compared with WT mice." (PMID 27075020, 2016). "σR agonists in mice promote the in vivo growth of a syngeneic lung cancer cell lines, which was accompanied by an increase in IL-10 and a decrease in interferon production in spleen cells and at the tumor site." (PMID 26056947, 2016). "The most intriguing finding was that the BCL1 tumor cells expressed the phenotype (CD1dhiCD5+) and cytokine profile (IL-10+) of B10 Bregs." (PMID 27959896, 2016). "Neutralizing IL-10 by anti-IL-10R mAbs significantly improves the anti-tumor immune response in certain animal models of cancer." (PMID 27833081, 2016). "Both TGFβ and IL-10 in the tumor microenvironment can be excreted by Tregs and tumor cells, thus mediating the immunosuppressive effect of Tregs." (PMID 27389040, 2016). "When tumor “relapse” occurs, the tumor cells again grow, kill the effector T cells, immunosuppress the host (likely by IL-10 secretion), and result in death." (PMID 27959896, 2016). "Based on these results, the EGFR-pathway appears to be more important for the formation of the tumor microenvironment than the Kras pathway, and IL10 appears to be crucial for the EGFRL858R-mediated tumor microenvironment." (PMID 26956044, 2016). "Taken together, these results are supportive of a tumour-promoting role for HMGB1 dependent on its ability to induce IL-10 secretion by M2-like macrophages in a RAGE-dependent manner." (PMID 27426915, 2016). "IFN-γ-deficient mice failed to respond similarly, and we found elevated levels of IFN-γ, IL-10, and IL-13 (among 15 examined) present in tumor lysate supernatants from wild-type mice treated with both antibodies than with either antibody alone." (PMID 27610613, 2016). "In recent studies, tumor-derived microvesicles were found to induce IL-10 expression in macrophages using a hyaluronan-dependent mechanism through the PI3K/Akt/mTOR pathway." (PMID 26884646, 2016). "Both TDLN and tumor-derived CD4+IFN-γ+ (Th1) cells were significantly elevated in IL-10−/− B16/F10 mice treated with the anti-Nrp-1 antibody." (PMID 27075020, 2016). "Alternatively they can promote tumor growth by generating interleukin-10 (IL-10) and transforming growth factor β (TGFβ) in situ, which help tumor cells to evade the immune system." (PMID 27389040, 2016). "RARi significantly suppressed TGF-β and IL-10, and enhanced IL-12 production by DC in a tumor model." (PMID 26941742, 2016).
tumor (continued). "Although soluble IL-10 secreted by the BCL1 tumor cells alone was insufficient to prevent T cell proliferation it likely contributed to an immunosuppressive milieu." (PMID 27959896, 2016). "In this study we have shown that following treatment with high salt the newly activated adherent macrophages induce anti-inflammatory (IL-10 and TGF-β) cytokines resembling MΦ2 phenotype in the tumor associated macrophages (TAM)." (PMID 27231721, 2016). "Cytokines, including interleukin (IL)-10 and ferritin, secreted by tumor-infiltrating immune cells and by the tumor itself are members of a larger scenario of a tumor-associated proteome." (PMID 27585656, 2016). "Utilizing our MB49 model, we showed that tumor-induced IL-10 production by immune cells in the TME inhibited the ability of DCs to induce an immune response." (PMID 28191451, 2016). "The source of high cervical production of IL-10 by tumor cells, keratinocytes, macrophages and Langerhans cells in SIL and CC cases has been demonstrated by an immunohistochemical analysis." (PMID 27115350, 2016). "Our study also used immunohistochemistry to detect the expression levels of TGFβ and IL-10 in the tumor microenvironment." (PMID 27389040, 2016). "Compared to that in peripheral blood, the level of IL-10-expressing B cells was further upregulated in resected tumor, while the level of CD4+ cytotoxic T cells was downregulated." (PMID 27136203, 2016). "Nonetheless, evidence suggests that many cytokines, such as TGF- β, IL-6, IL-10, etc. exert complex effects on tumor development." (PMID 26540574, 2016). "IL-10 is known to be secreted by tumor cells and promote immune-modulatory responses that favor tumor establishment and growth." (PMID 27413756, 2016). "Tumor growth facilitates the induction or recruitment of CD4+ regulatory T cells that secrete IL-10 and TGF-β and suppress effector CD8 T cell responses." (PMID 27075020, 2016). "STAT3 is known to be activated by several immunosuppressive cytokines commonly found in the tumor microenvironment, such as IL-10, which, in turn, further promotes the expression of these cytokines through a positive feedback loop." (PMID 27435207, 2016). "Tumor-associated macrophages were observed to upregulate the expression of B7-H4 through IL-6 and IL-10 in the tumor microenvironment." (PMID 27626488, 2016). "IL-9 impedes adaptive immunity responses and the maturation of T cells, while IL-10 can assist in tumor immune surveillance escape." (PMID 27169467, 2016). "This protective effect was associated with significant reduction in tumor-infiltrating FoxP3+ and IL-10+ Treg cells, and a corresponding increase in tumor-infiltrating CD4+ and CD8+ T cells that secreted IFN-γ." (PMID 26941742, 2016). "Based on the involvement of IL10 in the formation of tumor microenvironment and tumor development, we studied how IL10 increases EGFR expression." (PMID 26956044, 2016). "Co-treatment with dabigatran etexilate and cisplatin reduced levels of pro-tumorigenic cytokines, specifically IL-6 and IL-10, in the ascites compared to vehicle-treated mice, dramatically augmenting the anti-tumor efficacy of cisplatin treatment." (PMID 27852034, 2016). "IL-10 is an anti-inflammatory, immunosuppressive cytokine that favours tumour escape from immune surveillance and is involved in the generation of Treg cells with defined immunosuppressive functions." (PMID 26795765, 2016). "IL-10 is a cytokine with immunosuppressive properties which is frequently elevated in the tumor microenvironment and correlates with a bad outcome." (PMID 27600085, 2016). "Analysis of biopsy specimens from patients with tongue squamous cell carcinoma (TSCC) revealed increased frequency of CD19+IL-10+ Bregs in tumor tissue and metastatic lymph nodes compared to adjacent normal tissue." (PMID 27437104, 2016).